CTLA4 (cytotoxic T-lymphocyte associated protein 4)
Diseases named in the same sentence as CTLA4 in open-access papers (continued):
Sharing a sentence is not in itself a finding about the gene and the disease.
melanoma (continued). "Notably, in melanoma, while CTLA-4 blockade with ipilimumab was the first treatment to extend overall survival in patients with advanced melanoma in a randomized setting, anti-PD-1 mAb treatment (nivolumab) demonstrated higher efficacy in patients with smaller tumors." (PMID 38375475, 2024). "Two of the earliest publications to use CyTOF to characterize melanoma patient samples utilized the Helios platform to characterize peripheral blood mononuclear cells (PBMCs) or immune profiles of tumor biopsies from patients treated with anti-PD-1 monotherapy, or combined anti-PD-1 and anti-CTLA-4." (PMID 38217840, 2024). "Notably, pairing gene therapies with immune checkpoint inhibitors, which block proteins like PD-1 and Cytotoxic T-Lymphocyte Associated Protein 4 (CTLA-4) to restore immune activity, has significantly enhanced immune responses in cancers like melanoma and lung cancer." (PMID 39871848, 2024). "Notably, the combination of anti-LAG3 and anti-PD-1 may be more advantageous, as it has shown a better safety profile in advanced melanoma compared to the combination of anti-CTLA-4 and anti-PD-1." (PMID 39404378, 2024). "Building on this, Fässler, Mirjam, and their colleagues conducted a cohort experiment hypothesizing that pre-existing antibodies against more widespread antigens might correlate with the clinical outcomes of melanoma patients undergoing PD-1/PD-L1 and CTLA4 treatment." (PMID 39026661, 2024). "Therefore, cells with higher CTLA-4 expression are expected to have greater migratory capacity, since there will be greater signaling of chemokine receptors expressed in melanocytes, which play crucial roles in melanoma progression and metastasis." (PMID 39596391, 2024). "Thus, combinatory treatments with CpG-Stat3 siRNA and CTLA4 or PD-1 antibody may significantly boost the antitumor efficacies of CTLA4 or PD-1 antibody in treating B cell lymphoma and melanoma." (PMID 39618825, 2024). "In a melanoma mouse model induced by subcutaneous injection of B16 cells, activating nociceptors has been found to enhance the recruitment of NK, CD4+, and CD8+ T cells, which exhibit a less exhausted phenotype with reduced PD1 and cytotoxic T-lymphocyte-associated protein 4 (CTLA-4) expression." (PMID 38433844, 2024). "In malignant melanoma, the addition of CTLA-4 inhibitor after PD-1 inhibitor may improve PFS rates." (PMID 38611087, 2024). "Certain microbial compositions can enhance the body’s ability to fight melanoma by improving the response to immune checkpoint inhibitors like anti-PD-1 and anti-CTLA-4 therapies, suggesting that onco-microbiotic therapies could be tailored to optimize treatment outcomes." (PMID 39408717, 2024). "Future experiments combining MCL1 inhibitors with multiple ICIs (anti-PD-1 + anti-CTLA4 or anti-PD-1 + anti-LAG3) may help identify optimal treatment strategies for melanoma, as well as many other tumors where MDSCs prevent the efficacy of conventional therapies." (PMID 38459020, 2024). "Furthermore, BQ showed impressive single-agent efficacy in the immunocompetent B16F10 melanoma model, and combination treatment with BQ and dual immune checkpoint blockade (anti-CTLA-4 plus anti-PD-1) significantly prolonged mouse survival compared to either therapy alone." (PMID 37066260, 2024). "Outcomes for patients with melanoma have improved over the past decade with the clinical development and approval of immunotherapies targeting immune checkpoint receptors such as programmed death-1 (PD-1), programmed death ligand 1 (PD-L1) or cytotoxic T lymphocyte antigen-4 (CTLA-4)." (PMID 37507765, 2023). "As sex and age are well-known determinants of melanoma patient prognosis, a multivariable Cox PH analysis was applied, including the confounding effects of sex, age, and stage to compare the cumulative mortality in two log-CTLA4 level subgroups based on the cut-point in the respective AUS cohorts." (PMID 37197667, 2023).
melanoma (continued). "In conclusion, our data suggest that plasma IL-17 and TH17 cytokines may be a valuable baseline biomarker for response prediction and patient stratification in melanoma, specifically to predict a potential benefit of adding anti-CTLA-4 to anti-PD-1 antibodies upfront to therapy." (PMID 37525015, 2023). "Similarly, the CTLA-4 inhibitor antibody Ipilimumab was shown to be effective in inducing IL-2 expression as well as in improving NK cell cytotoxicity in a murine model of melanoma, even if the expression of CTLA-4 on NK cells remains controversial." (PMID 37298470, 2023). "Therefore, we tested whether melanoma cell secretome-mediated CTLA4 downregulation is regulated at the transcriptional level through FOXP3 in Treg cells." (PMID 37197667, 2023). "By competing with CD28 for binding of the costimulatory molecules CD80/86 expressed by antigen presenting cells, CTLA-4 was shown to reduce T cell activation and blockade of this receptor led to increased T cell activation and, critically, tumour regression in a mouse model of melanoma." (PMID 37139854, 2023). "Similarly, the analysis of another cohort from Cancer-Immu algorithm suggested that CHAC1 expression was also elevated in melanoma patients who responded to CTLA-4 blockade therapy, and patients with higher CHAC1 expression had increased overall survival or progression-free survival." (PMID 37553341, 2023). "Because CTLA-4 is expressed in immune cells such as Treg cells and activated T cells, we wondered whether we could observe similar or different trends in blood samples of melanoma patients." (PMID 37197667, 2023). "However, this combination may also lead to an increased frequency and severity of irAEs, as reported in clinical trials of anti-PD-1 (nivolumab) and anti-CTLA-4 (ipilimumab) combination therapy for melanoma." (PMID 37055838, 2023). "Moreover, for BRAF wild-type melanomas, current recommendations advocate using monoclonal antibodies (i.e., ipilimumab) that target immunological checkpoint proteins such as anti-PD-1 or CTLA-4 (cytotoxic T-lymphocyte antigen 4) in combination with anti-PD-1 therapy." (PMID 36747120, 2023). "Therefore, TGFβ in melanoma secretome may induce miR-155 intrinsically in Treg cells, leading to downregulating their CTLA4 expression." (PMID 37197667, 2023). "Subsequently, based on molecular biology experiments, we validated that silencing the expression of RAC1, an ERG composed of the risk signature, could restrain the proliferation and migration, promote apoptosis, as well as increase the expression of PD-1/PD-L1 and CTLA4 in melanoma cells." (PMID 37217516, 2023). "In this study, we combined functional analysis of short-term melanoma cell models with high dimensional flow cytometric profiling of matched tumor samples from melanoma patients progressing on PD1 inhibitor monotherapy or in combination with the CTLA4 inhibitor, ipilimumab." (PMID 36934113, 2023). "Of specific note, it has been well demonstrated that gut commensal bacteria such as Bifidobacterium and Bacteroidales could significantly improve tumor control of melanoma treated by anti-PD-L1 or anti-CTLA-4 via enhancing antitumor immunity response in mice models." (PMID 36911704, 2023). "CTLA-4 was highly expressed by tumour-infiltrating Treg cells in multiple models of transplantable syngeneic tumour cell lines of variable immunogenicity, as well as in human solid tumour subtypes including advanced melanoma, early-stage NSCLC, and renal cell cancer." (PMID 35814459, 2022). "Also, future evaluation of lower-dose anti-CTLA-4 may be considered to mitigate toxicity, potentially in combination with anti-PD-1/L1, which was shown in a melanoma model to enhance response of anti-CTLA-4 + RT11." (PMID 35440655, 2022).
melanoma (continued). "Furthermore, researchers have demonstrated that the silencing of PVR in melanoma increased sensitivity to combined anti-PD1/CTLA4 therapy, suggesting that targeting PVR could serve as a complement to current immunosuppressive therapies." (PMID 36552960, 2022). "Moreover, DCBLD2 upregulation was associated with worse PD1 outcomes in glioblastoma (ICB_Zhao2019_PD1) and melanoma (ICB_Riaz2017_PD1 and ICB_Liu2019_PD1), worse CTLA4 outcomes in melanoma (ICB_Nathanson2017_CTLA4), and worse PDL1 outcomes in the bladder (ICB_Mariathasan2018_PDL1)." (PMID 36034778, 2022). "Moreover, by analyzing tumor-infiltrating CD8+ T cells in melanoma patients treated with PD-1 or CTLA4 checkpoint immunotherapy, we found that T cells from nonresponders showed higher enrichment of lipid peroxidation and ferroptosis activation genes compared with responders." (PMID 35192544, 2022). "Therefore, CTLA-4 inhibitors also play an important role in tumor immunity, especially in melanoma." (PMID 35590394, 2022). "Inhibitors of immune checkpoint proteins, such as Cytotoxic T-Lymphocyte Associated Protein 4 (CTLA-4) and Programmed cell death protein 1 (PD1), are now established standards of care across a diverse range of solid and haematological cancers that include melanoma, lung cancer, and lymphomas." (PMID 35327375, 2022). "Unsurprisingly, elevated levels of CTLA-4 in association with poor prognosis has been found in NSCLC, breast cancer, nasopharyngeal carcinoma, small cell lung cancer (SCLC), prostate cancer, thymoma, melanoma, colorectal cancer (CRC), glioblastoma and osteosarcoma." (PMID 34980128, 2022). "Furthermore, the expression of ICIs between high- and low-risk melanoma patients were analyzed, indicating that the expression of immune-regulatory proteins (IRPs) such as PD-1 (PDCD1), PD-L1 (CD274), CTLA-4, HAVCR2 (TIM3), CD8, and LAG3 was significantly lower in the high-risk group (p < 0.05)." (PMID 35326741, 2022). "Notably, autophagy suppression in human melanomas resistant to CTLA-4 inhibitors, but not to PD-1, has been associated with the expression of cancer germline antigens." (PMID 36295867, 2022). "Consequently, ICIs, such as anti-PD-L1 monoclonal antibodies (mAbs-Atezolizumab, Avelumab, and Durvalumab), anti-PD-1 mAbs (Nivolumab and Pembrolizumab), and anti-CTLA-4 mAbs (Ipilimumab) led to marked therapeutic efficacy in melanoma, as well as lung, head and neck, and urothelial cancers." (PMID 35207516, 2022). "Another contemporary parallel study on anti-CTLA-4 therapy suggested that antibiotics dampen the antitumor effect of ICI, and supplementation with Bacteroides fragilis in germ-free or antibiotic-treated melanoma mice could augment anti-CTLA-4 therapeutic efficacy." (PMID 35488243, 2022). "Notably, a cohort of melanoma patients undergoing sequential anti-CTLA4 and anti-PD-1 had a survival advantage over both the corresponding monotherapies or the anti-PD-1 followed by anti-CTLA4." (PMID 35874810, 2022). "Finally, a retrospective Kaiser Permanente database search in Southern California revealed a higher 1-year incidence of uveitis in patients on ICIs who had a diagnosis of melanoma (1.2% overall, largely driven by CTLA-4 targets) over non-melanoma cancer (0.2%, Odds Ratio of 6.45)." (PMID 38983573, 2022). "Since 2015, when the FDA approved combination immunotherapy with ipilimumab (anti-CTLA-4) and nivolumab (anti-PD-1), the use of dual therapies has increased due to its higher efficacy than monotherapy against several cancers, including melanoma, non-small cell lung cancer, and colorectal cancer." (PMID 35433707, 2022). "However, only 33–44% of melanoma patients respond to monoclonal antibodies (mAb) against PD-1, and 58% of melanoma patients respond to combination therapy with mAb targeting PD-1 and CTLA-4." (PMID 35565329, 2022).
melanoma (continued). "In addition, a transcriptome study analyzing advanced melanoma patients treated with nivolumab (anti-PD-1) alone or combined with ipilimumab (anti-CTLA-4) showed high T cell infiltration and IFNγ signalling signatures in patients clinically responding to the therapy." (PMID 35251003, 2022). "Recent data have demonstrated that immunotherapies against immune checkpoints (e.g., CTLA-4 or PD-1) downregulate two main negative regulators of the anti-tumor immune response, resulting in durable anti-tumor responses in a subset of cancer patients, including those with melanoma." (PMID 36613491, 2022). "A cancer-antigen called MAGE-A is associated with CTLA-4 inhibitor resistance and is known to suppress autophagy, suggesting that autophagy induction may be used therapeutically as a way to improve the efficacy of CTLA-4 inhibitors in human melanomas." (PMID 36160153, 2022). "Besides, research has showed that a combination of anti-PD-1/PD-L1 antibody and CTLA-4 inhibitor can improve treatment effects of patients with advanced melanoma, which was approved by the FDA in treating BRAF V600 E wild-type patients with unresectable or metastatic melanoma." (PMID 34876903, 2021). "In addition to the anti-CTLA-4 antibody ipilimumab in melanoma, clinical studies of the anti-PD-1 antibody nivolumab in advanced HCC patients have also proven this antibody to be efficient in phase I/II clinical trials with satisfactory safety and response data." (PMID 33596985, 2021). "This means that blocking CTLA-4 with Ipilimumab (anti-CTLA-4 monoclonal antibody, which has been accredited as checkpoint inhibitor for melanoma treatment) can significantly activate the molecular cascade, which may help enhance the immune response to tumor cells." (PMID 35111680, 2021). "While human melanoma in the TCGA shows a reverse relationship between G9a expression levels and immune signature genes, mouse studies in melanoma found that G9a inhibition, in combination with anti-PD-1 or anti-CTLA-4, increased survival compared to immunotherapy alone." (PMID 34691767, 2021). "In the present study, we established a method based on the immune subtype classification of melanoma to identify a tumor immune-relevant (TIR) signature, which could predict the survival outcome as well as the response to anti-CTLA4 treatment in patients with melanoma." (PMID 33753855, 2021). "CTLA-4 is another checkpoint pathway that may be usurped by human tumors, and in which blockade using a mAb can translate into therapeutic activity, as has been shown in melanoma." (PMID 32601377, 2021). "In breast cancer, colon cancer, and melanoma, inhibition of CSF-1/CSF-1R signaling using an anti-CSF-1R antibody can regulate both the number and the function of MDSCs, induce antitumor T-cell responses and tumor regression when combined with CTLA-4 blockade therapy." (PMID 35003065, 2021). "Moreover, upon exposure to the HDACi entinostat in combination with azacytidine, the syngeneic mouse melanoma models displayed improved rates of response to both anti-PD-1 and anti-CTLA-4 immunotherapies, and the tumors were eradicated in 80% of the experimental animals." (PMID 34575678, 2021). "Additionally, T cell accumulation in the tumor during anti-CTLA-4 or IL-2 immunotherapy leads to an increase in EZH2 expression in melanoma cells, which further decreases their immunogenicity and antigen presentation, thus contributing to intrinsic resistance to these immunotherapies." (PMID 34944799, 2021). "Furthermore, recent studies searching for the effective immunotherapies in cancer and found that ICIs were successful cancer treatments, particularly in metastatic urothelial cancer and melanoma where anti-CTLA-4/PD-1/PD-L1 antibodies have found widespread application." (PMID 34552879, 2021). "Furthermore, we showed that melanoma patients that were not responsive to anti-CTLA-4 therapy had tumors harboring a greater copy number loss of IFN-γ signaling genes." (PMID 34830176, 2021).
melanoma (continued). "Moreover, when applied to melanoma patients treated with the CTLA4 antibody, ipilimumab, the TIR signature could predict the response to ipilimumab and the survival." (PMID 33753855, 2021). "Moreover, the viral defense gene signature in tumor samples significantly correlated with the long-term clinical outcome of melanoma patients treated with anti-CTLA4, and combination of DNMTi with anti-CTLA4 in the murine B16 melanoma model showed favorable therapeutic response." (PMID 33403469, 2021). "Therefore, we next examined whether the refined TRS could predict ICB clinical response utilizing two cohorts (Allen2015 and ERP105482) of melanoma patients treated with anti-PD1 or anti-CTLA4 ICB therapies." (PMID 34804045, 2021). "Thus, we used a cohort of melanoma patients who received anti-CTLA4 therapy and urothelial cancer cohorts of patients who received anti-PD-1 therapy (IMvigor210) to perform a complementary evaluation of the ability of HSPA7 to predict the immunotherapy response." (PMID 34354698, 2021). "In recent years, research on immune checkpoint inhibitors of PD-1, PD-L1, and CTLA-4 have become a hot topic in the field of cancer because of their remarkable efficacy in prolongation of the survival of patients with non-small cell lung cancer, melanoma, and renal cell carcinoma." (PMID 34391428, 2021). "Based on this signature, the tumor immune microenvironment (TME) of melanoma was characterized, and the result was found that patients in the high-risk group had lower CD8 T cell infiltration and immune checkpoint expression (PD-1, PD-L1, CTLA4), as well as higher M0/M2 macrophage infiltration." (PMID 34805163, 2021). "In the absence of an appropriate ICI-based colon cancer dataset, we hope that combined with different immunotherapy regimens (anti-PD1/L1 or anti-CTLA-4) across different malignancies (Melanoma and Urothelial cancer) to verify the effects of m6Sig score could further strengthen our conclusion." (PMID 33500720, 2021). "Consequently, melanoma samples with a lower CTLA4 promoter methylation level might exhibit a certain immune cell infiltration pattern contributing to response to anti-CTLA-4 immunotherapy." (PMID 33196890, 2021). "Indeed, it has revealed that therapies such as ipilimumab and pembrolizumab which target the CTLA4 and PD-1 immune checkpoints, respectively, have raised the 3 years survival of patients with melanoma to 70%, and overall survival (>5 years) to 30% in phase III clinical trials." (PMID 33849069, 2021). "Similarly, CTLA-4 has been found to be expressed on melanoma cells and to drive tumor formation." (PMID 32429485, 2020). "This may be explained by several differences, including the mouse strain (BALB/c versus C57/BL6), cancer model (renal cell carcinoma versus melanoma and lung carcinoma models) and modalities of immunotherapy (anti-CTLA-4 combined with other immunostimulants versus anti-PD-1)." (PMID 33170123, 2020). "Thus, increased representation of F. prausnitzii in one’s microbiome could benefit melanoma patients on combination therapy with anti-CTLA-4 and anti-PD-1 therapy." (PMID 32944086, 2020). "This therapy based on blockade of such molecules as CTLA-4 (cytotoxic T lymphocyte-associated antigen), PD-1 (programmed cell death receptor type 1), or PD-1 ligand (PD-L1) brings a new hope for patients with non-small cell lung cancer (NSCLC), melanoma, or head and neck squamous carcinoma." (PMID 33330040, 2020). "Especially, the S524L substitution in CDH6 has been predicted to be a strong neo-antigen, peptides with such substitution could be utilized as potent adjuvants to trigger stronger anti-melanoma immunity when co-treated with other immuno-therapeutics such as anti-PD-1/L1 or anti-CTLA4 Abs." (PMID 33204327, 2020).